CDKN2A (cyclin dependent kinase inhibitor 2A)
Diseases named in the same sentence as CDKN2A in open-access papers (continued):
Sharing a sentence is not in itself a finding about the gene and the disease.
melanoma (continued). "Germline CDKN2A mutations in familial melanoma-prone families showed diverse mutation types and variable pancreatic cancer distribution, suggesting genetic heterogeneity." (PMID 38666907, 2024). "On the other hand, mutations in the CDKN2A gene are mainly associated with an elevated risk of oncological conditions, such as melanoma and pancreatic cancer, entities identified through specific genetic tests in about 38% of families with melanoma history." (PMID 38792946, 2024). "The penetrance of melanoma in families with CDKN2A pathogenic variants is estimated to range from 58 to 92% by age 80, and the penetrance of pancreatic cancer is estimated at 17–21% by age 70 to 75 in Western Countries." (PMID 38961426, 2024). "One study showed a tendency toward better melanoma control in patients with CDKN2A mutations treated with ICI." (PMID 38534309, 2024). "Using CRISPR knockout libraries in isogenic human and mouse melanoma cell lines, we determined several nucleotide metabolism genes essential for the survival of cells with loss of p16/CDKN2A." (PMID 38626341, 2024). "In 1994, a mutation of the CDKN2a/MTS1/INK4A gene located on chromosome 9p21 was found in patients with melanoma." (PMID 38396841, 2024). "Even though CDKN2A heterozygous deletions are sufficient to confer a 67% risk of melanoma development, it was found that the mechanisms responsible for oncogenesis and tumor progression required clarification at the present time." (PMID 38667459, 2024). "The main hereditary factors contributing to melanoma development are mutations in the CDKN2A or CDK4 gene, polymorphism of MC1R, and many nevi." (PMID 39340537, 2024). "In FPC families, CDKN2A mutations were identified in 21.4% of cases, and in patients with both pancreatic adenocarcinoma and melanoma, germline CDKN2A mutations (I49S and M53I) were found, with I49S showing impaired binding to CDK4." (PMID 38666907, 2024). "CDKN2A germline mutations stand as the predominant genetic alterations associated with hereditary melanoma, accounting for approximately 40% of cases within this subtype 2." (PMID 39659584, 2024). "Primary melanomas with BRAF V600E mutations indeed had more frequent inactivating mutations of the CDKN2A gene (45.2 vs. 27.7%, P = 0.027, Fisher's exact test), consistent with early corruption of critical cell-cycle checkpoint components triggered by OIS." (PMID 38371417, 2024). "On the other hand, in agreement with previous studies, in Veneto, the presence of at least one MPM case in melanoma-prone families increased the frequency of pathogenic CDKN2A variants to 31.6%." (PMID 39596909, 2024). "Several high-penetrance melanoma susceptibility genes, including CDKN2A and CDK4, are associated with familial melanoma syndromes characterized by an autosomal dominant inheritance pattern." (PMID 39200315, 2024). "A family history of CM poses the highest risk for the development of melanoma and germline mutations in some high-penetrance CM susceptibility genes have been described, namely in CDKN2A, CDK4, MITF, TERT, BAP1, and POT1." (PMID 38730639, 2024). "Individuals with pathogenic variants affecting biologically relevant CDKN2A isoforms (i.e., p16INK4A and p14ARF) are recommended for surveillance for both melanoma and pancreatic cancer." (PMID 38961426, 2024). "We further validated our findings in another immunotherapy-resistant tumor model, YUMM1.7, a mouse melanoma line containing human-relevant mutations (BrafV600E; Cdkn2a−/− Pten−/−; Tyrosinase:CreERT2)." (PMID 38451948, 2024). "The Norwegian study identified seven distinct CDKN2A PVs across 18 different families, all of which were associated with a high risk of melanoma and a potential risk of pancreatic cancer." (PMID 38822936, 2024). "Common aberrations, which have influence on melanoma development, include CDKN2A (p16 coding gene) mutations and deletions as well as CDK4/6 genes and CCND1 (cyclin D1 coding gene) amplification." (PMID 39598629, 2024).
melanoma (continued). "Although CDKN2A mutations and its modulators increase the risk of melanoma, others like host, genetic, and environmental factors also increase that risk." (PMID 37504268, 2023). "While only 5–12% of melanomas are thought to be hereditary, approximately 40% of hereditary melanomas are attributable to CDKN2A mutations, making CDKN2A the most commonly mutated gene responsible for an autosomal dominant pattern of hereditary melanoma." (PMID 38076247, 2023). "In our cohort, out of 115 patients referred to genetic counseling for melanoma, 25 tested positive (21.7%) for critical mutations: CDKN2A (n = 12), MITF (n = 3), BAP1 (n = 1), MC1R (n = 3), PTEN (n = 1), TYR (n = 2), OCA2 (n = 1), and SLC45A2 (n = 2)." (PMID 37568588, 2023). "Matching with our findings, CDKN2A mutations were predisposing to multiple nerve sheath tumors, melanoma, and internal malignancies." (PMID 37626750, 2023). "We observed similar phenotypic differences in tumor burden when comparing WT and Atg12ECKO or Atg9ECKO mice inoculated with B16‐F10 or the immunogenic YUMMER 1.7 melanoma cells, carrying the BrafV600E/Pten−/−/Cdkn2a−/− mutations, respectively." (PMID 38009521, 2023). "Cyclin-dependent kinase inhibitor 2A (CDKN2A) was the first high-penetrance melanoma gene identified and encodes two distinct proteins (p16 and p14ARF), both acting in cell cycle regulation." (PMID 37958811, 2023). "In this prospective monocentric study, we assessed general melanoma awareness and UV protection habits in at-risk patients (≥100 nevi, ≥5 dysplastic nevi, known CDKN2A mutation, and/or positive family history) and melanoma patients using questionnaires." (PMID 37207151, 2023). "CDKN2A mutations are more common in melanomas that develop in people with fair skin and in people who have a history of sun exposure." (PMID 37504268, 2023). "The somatic deletion and mutation of the CDKN2A locus are among the most common genetic alterations in melanoma, responsible for the progression from precursor lesions to invasive melanoma." (PMID 36834954, 2023). "While some families with germline CDKN2A mutations are prone to develop just melanomas, others develop both melanomas and astrocytomas or even other nervous-system neoplasms." (PMID 36980355, 2023). "Individuals with germline mutations in the CDKN2A, a tumor suppressor gene, have a very high lifetime risk of developing CM, this mutation being encountered in up to 40% of melanoma-prone families." (PMID 37958863, 2023). "For example, CDKN2A mutations (located on chromosome 9) are found in 3-20% of the families with a history of melanoma." (PMID 36676131, 2023). "Generally, pathogenic mutations in the CDKN2A gene are linked to a lifetime melanoma risk ranging from 28% to 67% before the age of 80." (PMID 38137564, 2023). "Studies reported that people with certain MC1R variants are at an increased risk of developing melanoma, and that this increased risk is more pronounced in people with CDKN2A mutations." (PMID 37504268, 2023). "And the epigenetic (DNA methylation) or genetic (mutation) changes of CDKN2A lead to the initiation of ovarian cancer and melanoma." (PMID 37857018, 2023). "By comparison and looking at another melanoma high-penetrance gene, in the Leeds Melanoma Cohort, CDKN2A variant carriers have an average age of onset of 50 years (based on data included in Ref." (PMID 36539277, 2023). "Germline mutations that significantly increases the life-time risk of developing melanoma include CDKN2A, CDK4, BAP1, TERT, MITF, MC1R, and POT1." (PMID 38076247, 2023). "Germline mutations in the CDKN2A gene are the most common cause of hereditary melanoma, accounting for about 20–40% of melanoma cases in families." (PMID 37504268, 2023).
melanoma (continued). "Seven out of eight individuals with a CDKN2A germline mutation previously underwent curative treatment for a melanoma (<T1)." (PMID 36982172, 2023). "Compared to the 2.6% lifetime risk of developing melanoma in the US White population, patients with germline CDKN2A mutation increases that risk to 28 to 76% depending on the presence of other factors." (PMID 38076247, 2023). "Atypical/dysplastic nevi, higher numbers of typical nevi, and poor tanning ability and/or tendency to sunburn have all been found as host-modifying variables in melanoma-prone families with CDKN2A mutations." (PMID 37504268, 2023). "The Dutch Working Group on Melanoma also considers MM screening in patients with first- and second-degree relatives with melanoma-pancreatic carcinoma syndrome or CDKN2A mutation, 1–2 times per year, starting at 12 and 20 years old, respectively." (PMID 37370677, 2023). "The high deletion frequency of CDKN2A has been shown to be associated with a variety of tumors such as melanoma, lung cancer, head and neck cancer, pancreatic cancer, breast cancer, osteosarcoma, ovarian cancer." (PMID 36961395, 2023). "A splice site mutation in CDKN2A, found in a family with melanomas, neurofibromas, and multiple dysplastic nevi, was reported to cause the skipping of exon 2, which encodes more than 50% of the p16INK4A and p14ARF proteins." (PMID 37875914, 2023). "The overall risk of developing melanoma in an 80-year-old individual with a family mutation of CDKN2A has been found to be increased by 58% in Europe, 76% in the US, and 91% in Australia." (PMID 37568588, 2023). "Among the 16 probands with a familial history of cancer, including cases of pancreatic cancer and melanoma, clinically significant genetic variants of CDKN2A were identified in five (31%) cases." (PMID 38137564, 2023). "In a single NRAS mutant melanoma patient, this combination was found to be effective, perhaps related to CDKN2A mutation status." (PMID 37126527, 2023). "In melanoma with CDKN2A germline mutations, there are usually somatic mutations in BRAF and NRAS genes, NRAS mutations being the most common ones." (PMID 36805510, 2023). "The protein p16, also called inhibitor of kinase 4, A (INK4A) or cyclin-dependent kinase inhibitor 2A (CDKN2A), is encoded by CDKN2A, the commonest known susceptibility gene for melanoma." (PMID 37522264, 2023). "Data regarding the frequency of germline mutations in the CDKN2A gene for Brazilian individuals fulfilling clinical criteria for familial melanoma are scarce and differ according to the region studied and the adopted criteria, varying from 0% to 14%." (PMID 37958811, 2023). "Pathogenic variants in CDKN2A correspond to 10% of families with two cases of melanoma and 30 to 40% of families with 3 or more cases, showing association with pancreatic cancer." (PMID 37895483, 2023). "CDKN2A also encodes another growth suppressor, ARF, but ARF function is less commonly impaired by familial melanoma mutations in the gene than that of p16." (PMID 37522264, 2023). "It has been shown that in melanoma patients with BRAFV600 mutations the expression of MIR31HG negatively correlates with the expression of CDKN2A, encoding p16INK4A." (PMID 37325482, 2023). "In one study, the risk of melanoma in CDKN2A mutation carriers was approximately 14% by age 50 years, 24% by age 70 years, and 28% by age 80 years." (PMID 38076247, 2023). "The CDKN2A cluster of patients was the first to be associated with a higher risk of developing familial melanomas, as this mutation can be found in up to 25% of Caucasian families with multiple melanomas." (PMID 37568588, 2023). "CDKN2A, which encodes p16(INK4A) and p14(ARF) cell cycle-related tumor suppressors, was the first familial susceptibility gene and among the most highly penetrant with 30-90% risk of melanoma by age 80 years." (PMID 37841001, 2023).
melanoma (continued). "The CDKN2A gene, frequently mutated in melanoma (35% of patients in TCGA cohort), was more frequently altered in NR patients." (PMID 37739939, 2023). "In general, CDKN2A GPV is found in 10 to 40% of melanoma-prone families and is associated with an increased number of family members affected early age at melanoma diagnosis, MPM, and pancreatic cancer." (PMID 37958811, 2023). "Melanoma pancreatic syndrome or familial atypical multiple mole melanoma (FAMMM) (OMIM# 606719) is a hereditary tumor syndrome characterized by an increased risk of melanoma and pancreatic cancer in individuals with a germline mutation in the CDKN2A gene." (PMID 38137564, 2023). "In melanoma, CDKN2A mutations are often found in combination with other genetic changes, such as BRAF mutations." (PMID 37504268, 2023). "First, we confirm that CDKN2A does represent the most common germline mutation in our familial melanoma cohort, as reported in the other cohorts of patients from different Italian regions." (PMID 37568588, 2023). "Familial cutaneous malignant melanoma, comprising ~10% of all melanomas, displays mutations of the tumour suppressor gene Cyclin Dependent Kinase Inhibitor 2A (CDKN2A)." (PMID 36614303, 2023). "The presence of CDKN2A mutations can influence the prognosis and treatment of melanoma, and they are often taken into consideration when determining the appropriate course of treatment." (PMID 37504268, 2023). "It is well known that germline CDKN2A inactivation can lead to a high predisposition for melanoma and pancreatic cancer." (PMID 36531022, 2022). "In particular, CDKN2A represents a key melanoma susceptibility gene and its mutations are demonstrated in 20–40% of familial melanoma." (PMID 35456025, 2022). "It is estimated that ~10% of all melanoma cases diagnosed in 2002 were hereditary, with 40-60% of them occurring due to the mutation of the gene coding for CDKN2A." (PMID 35465855, 2022). "A later study utilizing melanoma cell lines across different stages of melanoma progression implicated sequential loss of Cyclin Dependent Kinase Inhibitor genes CDKN2A and CDKN2B with CA." (PMID 36276131, 2022). "CDKN2A is often mutated in familial melanoma and is one of the major melanoma susceptibility genes, with its mutation allowing cells to escape from cell cycle arrest." (PMID 35993275, 2022). "Given the risk for melanoma is impacted by environmental factors such as UV exposure, a deeper understanding of the behavioral changes among individuals with a CDKN2A PV is important in tailoring medical management and targeting surveillance efforts." (PMID 35372037, 2022). "The largest proportion of hereditary melanoma cases are due to pathogenic variants (PVs) in the CDKN2A/p16 gene, which account for 20%-40% of familial melanomas and confer up to a 30%-70% lifetime risk for melanoma in individuals with these variants." (PMID 35372037, 2022). "Mutations in the CDKN2A, instead, are common in all melanoma subtypes, suggesting that the breakdown of the senescence barrier is a required step in the progression of melanoma regardless of the driver mutation." (PMID 36077374, 2022). "The CDKN2A (Cyclin-Dependent Kinase Inhibitor 2A) gene mutation, present in 25–50% of familial melanoma cases, has been associated with an elevated risk of melanoma." (PMID 36286442, 2022). "Of note, loss of 9p21 – where CDKN2A/B reside - is prevalent in melanoma and has recently been associated with primary resistance to ICI treatment." (PMID 36276131, 2022). "A mutation in the CDKN2A gene is identified in melanomas of patients whose time to progression was shorter than the median for patients treated with BRAF inhibitors." (PMID 35565444, 2022). "Human melanoma and pancreatic carcinoma are tumors in which CDKN2A loss of function is extremely frequent." (PMID 35456025, 2022).
melanoma (continued). "The cyclin-dependent kinase inhibitor A and B (CDKN2A/B) gene encodes for three tumor suppressor proteins, the loss of which has been demonstrated to contribute to spontaneous development of melanomas in CDKN2A/B knockout mice." (PMID 36686824, 2022). "Patients with familial atypical multiple mole melanoma (FAMMM), a hereditary cancer syndrome caused by mutation of cyclin‐dependent kinase inhibitor 2A (CDKN2A), are known to have a significantly higher risk of melanoma and pancreatic cancer." (PMID 35932099, 2022). "Variants in MC1R, often but not always associated with a red hair phenotype, can act as a modifier gene for CDKN2A mutation carriers, as well as their known effect as an independent low-penetrance susceptibility gene for melanoma." (PMID 35372037, 2022). "Germline, (inherited, in contrast to somatic or acquired), mutations of CDKN2A are the most common cause of inherited susceptibility to melanoma and is implicated in 25–40% of patients with familial atypical multiple mole melanoma (FAMMM; OMIM #155601)." (PMID 35123577, 2022). "CDKN2A gene mutations are responsible for the majority of hereditary melanomas; indeed, over half of individuals with multiple primary melanomas carry mutations in this gene." (PMID 36614041, 2022). "The deletion of Cdkn2a, a mutation that frequently occurs in all known melanoma genetic subtypes, was found associated with the activation of mTORC2/Akt signaling although the precise mechanisms underlying this event where not fully elucidated." (PMID 36077374, 2022). "According to one study, POT1 seems to be one of the most commonly mutated genes in hereditary melanoma, along with CDKN2A." (PMID 35465855, 2022). "Regarding molecular data, mutations in the melanoma susceptibility gene, CDKN2A, were studied in only four (6.9%) patients, and only one carried the variant V59G of CDKN2A." (PMID 35566480, 2022). "It has been described as a major gene involved in the development of sporadic melanoma, and its variants have been associated with the increased penetrance of CDKN2A mutations in melanoma-prone families." (PMID 35158770, 2022). "In a genotype-phenotype correlation study, multiple primary melanomas were the most predictive factor for presence of a CDKN2A mutation." (PMID 35372037, 2022). "Multiple and/or dysplastic nevi are not restricted to inherited syndromes and are considered a strong risk factor for both sporadic melanoma and melanoma in CDKN2A carriers." (PMID 35372037, 2022). "The rs11515 variant is located in the 3′-untranslated region (UTR) of the CDKN2A gene, and is known to be associated with a number of different types of cancer, including breast cancer, glioblastoma, melanoma, and colorectal cancer." (PMID 35743641, 2022). "A study of the Melanoma Genetics Consortium (GenoMEL) showed that the presence of PC in individuals with familial melanoma is a strong predictor of a pathogenic CDKN2A variant." (PMID 35761384, 2022). "Genetic predisposition accounts for nearly 10% of all melanoma cases and has been associated with a dozen moderate- to high-penetrance genes, including CDKN2A, CDK4, POT1 and BAP1." (PMID 35085295, 2022). "Among 66 families with familial melanoma in which PC occurred, as many as 49 (74%) had a CDKN2A mutation." (PMID 35761384, 2022). "CDKN2A on chromosome 9p21 encodes p16INK4a and p14ARF proteins, whose mutation or deletion are closely related to various tumors, such as pancreatic cancer, thymic cancer, melanoma, lung cancer, and others." (PMID 36060256, 2022).